ATG4D (autophagy related 4D cysteine peptidase)
Diseases named in the same sentence as ATG4D in open-access papers (continued):
Sharing a sentence is not in itself a finding about the gene and the disease.
tumor (15 papers, 2017 to 2025). "Immunohistochemical (IHC) staining revealed that ATG4D protein levels were significantly elevated in tumor tissues compared to normal osteoblasts or osteoclasts." (PMID 40883962, 2025). "The distribution of ATG4D protein expression in normal and tumor tissues was further analyzed, indicating that 36 tumor tissues exhibited high ATG4D levels, while 50 tumors displayed low ATG4D expression." (PMID 40883962, 2025). "Further subgroup analysis stratified patients by gender, age, and tumor location to assess the correlation between ATG4D expression and clinical outcomes." (PMID 40883962, 2025). "While previous studies have indicated that ATG4D expression can be influenced by the tumor microenvironment, which plays a significant role in cancer metastasis." (PMID 40630202, 2025). "A pan-cancer analysis using RNA-Seq demonstrates the variability of ATG4D expression across various tissue and tumor types." (PMID 38920354, 2024). "On the other hand, ATG4D was considered as a tumor suppressor in colorectal carcinogenesis since reduced ATG4D expression was observed in adjacent normal cells." (PMID 31083460, 2019). "Nevertheless, in regard to the specific tumor microenvironment, we found statistically significant downregulation of ATG4D expression in adjacent normal cells in patients with high tumor stages and high values for regional lymph nodes." (PMID 30374741, 2018). "Changes in autophagy regulation, which affect tumor cell interactions with their surroundings and immune evasion, have been highlighted as mechanisms by which ATG4D might influence metastasis." (PMID 40630202, 2025). "However, ATG4D expression is lower in tumor‐adjacent normal tissues of CRC patients, suggesting a potential tumor‐suppressive role." (PMID 40883962, 2025). "ATG4D is also a target of the tumor suppressing microRNA, MIR101." (PMID 38920354, 2024). "Meanwhile, ATG4D was considered a tumor suppressor in colorectal carcinogenesis." (PMID 36980240, 2023). "A large body of evidence suggests that inhibition of the activity of other ATG4 family members, including ATG4A, ATG4B and ATG4D, could suppress tumor progression and enhance chemosensitivity or the efficacy of radiotherapy." (PMID 31291988, 2019). "Furthermore, in regard to the ATG4D gene, we observed the influence of tumor microenvironments on gene expression in adjacent colon mucosa." (PMID 30374741, 2018). "In this context, ATG4D and autophagy may be promoting progression in an already established tumor." (PMID 38920354, 2024). "From the results, we noticed that tumor cells highly expressed AUP1 significantly correlated with proliferation marker (MCM2, MCM6), PI3K-AKT-MTOR pathway (Akt1, TSC1, mTOR, Foxo1), and autophagy signaling (Atg3, Atg4B, Atg4D, Atg7, Atg9A, Atg16L1) in IDH wildtype tumor cells." (PMID 37029364, 2023). "N = 1 is associated with a lack of difference in levels of expression of ATG4D between healthy and tumor cells." (PMID 30374741, 2018). "To understand the mechanism of this differential effect, we found that ferroptosis inducers upregulate mRNAs encoding multiple direct and indirect autophagy stimulators, such as ATG16L2, ATG9A, ATG4D, GABARAP, SQSTM/p62, SEC23A and BAX, in tumor cells growing in 2D but not in 3D culture." (PMID 37658069, 2023).
cancer (14 papers, 2017 to 2025). A tumor composed of atypical neoplastic, often pleomorphic cells that invade other tissues. "The ATG4 family (ATG4A, ATG4B, ATG4C, and ATG4D) encodes proteases essential for autophagy, a process implicated in cancer progression and drug resistance." (PMID 40883962, 2025). "Despite its apparent role in cancer development and progression, increased levels of ATG4D expression have also been associated with prolonged lifespan in humans and Drosophila." (PMID 38920354, 2024). "ATG4C and ATG4D have also been implicated in cancer biology." (PMID 31083460, 2019). "Autophagy-related proteins, including ATG4D, have been associated with the regulation of EMT and interactions with key signaling pathways, such as mTOR, that regulate cancer progression." (PMID 40630202, 2025). "Abnormal DNA methylation of ATG4D profoundly contributes to various human diseases, including cancers." (PMID 40949798, 2025). "MIR101 can reduce levels of ATG4D mRNA, which supresses autophagy, promotes apoptosis, and sensitizes some cancer types to chemotherapy treatments." (PMID 38920354, 2024). "Further investigations are needed to delineate the roles of ATG4D in cancer progression and treatment response." (PMID 38920354, 2024). "ATG4 (ATG4A, ATG4B, ATG4C and ATG4D), a cysteine protease family, plays a crucial role in autophagy signaling and correlated with cancer progression in different types of cancers." (PMID 37038218, 2023). "In normal cells of patients with advanced cancer stages, we found statistically significant downregulation of the ATG4D gene." (PMID 30374741, 2018). "Similarly, promoter hypermethylation of ATG4D, ATG2B, ATG9A, and ATG9B genes has been demonstrated in most invasive ductal carcinomas (IDC), and this enhanced methylation was associated with the cancer grade, reduced gene expression, and lymph node metastasis." (PMID 40949798, 2025). "Although ATG4 family members are important for autophagosome formation and maturation, the specific role of ATG4D in autophagy regulation in cancer cells remains unclear." (PMID 40883962, 2025). "The observed variability in ATG4D-related effects in various cancer contexts may also be due in part to the different genetic backgrounds of the cell line models used for the studies." (PMID 38920354, 2024). "Of the four human ATG4 homologs, ATG4D is the most frequently altered in cancers." (PMID 38920354, 2024). "Apart from ATG4B, other mammalian ATG4 homologues may also be potential therapeutic targets for cancer, particularly ATG4D, which plays a notable role in apoptosis." (PMID 31083460, 2019). "Furthermore, studies have shown that inhibition or silencing of ATG4D could sensitize cancer cells to chemotherapeutic drugs." (PMID 31083460, 2019). "Among them, ATG4D, a member of the autophagy-related protein 4 (ATG4) family, serves as an intriguing nexus between autophagy and apoptosis across multiple cancers." (PMID 38240686, 2024). "Three of the autophagy targets of miR-101 (RAB5A, ATG4D and STMN1) have been validated in human cancer models." (PMID 29089869, 2017). "Still, when sorted by statistical significance, ATG4D, ATAD3A, and MRPL41 are found in less apical positions in the lists of the top 200 genes negatively correlated with GALC expression in the other human cancer data sets investigated here." (PMID 38474307, 2024). "These alterations in ATG4D, which can include changes in methylation, increases and decreases in transcript and protein levels, as well as alterations in the protein itself, are not consistent between various cancer types." (PMID 38920354, 2024). "Furthermore, after the blockade of PPARγ/SOD2 pathway, ATG4D was located in mitochondria to activate the process of mitophagy, contributing to the increase of mitochondrial ROS production, damage of MMP stabilization and promotion of cancer cell apoptosis." (PMID 35186942, 2021).
cancer (continued). "Furthermore, after inhibiting the expression of ATG4D by siRNA in cells, mitochondrial membrane potential and cell apoptosis were all decreased, no matter whether Rosiglitazone or T0070907 was used to treat cancer cells or not." (PMID 35186942, 2021). "Within the EBV-positive subgroup, higher expression of ATG4B and ATG4D was more prevalent in regional carcinomas compared to localized or distant carcinomas (P = 0.031 for ATG4B; P = 0.048 for ATG4D), though this trend was not significant in the overall cohort (P = 0.061 for both ATG4B and ATG4D)." (PMID 40630202, 2025).
neurodevelopmental disorder (4 papers, 2023 to 2024). A behavioral and cognitive disorder with onset during the developmental period that involves impaired or aberrant development of intellectual, motor, or social functions. "Deficiency or mutation of ATG4D causes cerebellar neurodegeneration and neurodevelopmental disorders." (PMID 38167306, 2024). "ATG4D has been implicated in a rare autosomal recessive syndromic neurodevelopmental disorder in humans." (PMID 38920354, 2024). "In this study, we report three individuals from two unrelated families with bi-allelic loss-of-function variants in ATG4D presenting with a neurodevelopmental disorder characterized by speech and motor impairment with variable disease severity and progression." (PMID 36765070, 2023). "At the same time, in a recently published paper, it was found that bi-allelic loss-of-function variants in ATG4D is the cause of syndromic neurodevelopmental disorders." (PMID 37373039, 2023). "The clinical, bioinformatic, and functional data suggest that bi-allelic loss-of-function variants in ATG4D contribute to the pathogenesis of this syndromic neurodevelopmental disorder." (PMID 36765070, 2023). "In this study, we report three individuals from two unrelated families presenting with a neurodevelopmental disorder associated with bi-allelic variants in ATG4D." (PMID 36765070, 2023). "Notably, genetic variations in human ATG4D were implicated in a heritable neurodevelopmental disorder." (PMID 38920354, 2024). "In summary, we have identified ATG4D as a candidate gene for a syndromic neurodevelopmental disorder." (PMID 36765070, 2023).
neurological disease (3 papers, 2015 to 2024). "Lagotto Romagnolo breed dogs develop a progressive neurological disease with intracellular vacuolar storage when homozygous for a variant in the autophagy-related gene 4D (ATG4D)." (PMID 33016245, 2020). "Here we discuss the evidence connecting ATG4D to neurological diseases and other pathologies and summarize its roles in both autophagy-dependent and autophagy-independent cellular processes." (PMID 38920354, 2024). "Our study describes a previously unknown canine neurological disease with particular pathological features and implicates the ATG4D protein as an important autophagy mediator in neuronal homeostasis." (PMID 25875846, 2015).
neurodegenerative disease (2 papers, 2023 to 2024). A disorder of the central nervous system characterized by gradual and progressive loss of neural tissue and neurologic function. "ATG4D plays an important role in neuron homeostasis, and mutations in ATG4D have been implicated in heritable neurodegenerative diseases in humans and canines." (PMID 38920354, 2024). "Taken together, our results revealed an important link between ATG4 factors and healthspan and lifespan, and offered ATG4, in particular ATG4D and ATG4B, as potential target for intervention of neurodegenerative diseases." (PMID 37373039, 2023).
infection (1 paper, 2019). The state of being infected such as from the introduction of a foreign agent such as serum, vaccine, antigenic substance or organism. "Even though ATG4D expression was slightly (~2-fold) sustained by 4 hpi and throughout the infection period, TP53INP1 was repressed by 2.6-fold at 8 hpi." (PMID 31969876, 2019).
neurogenetic disease (1 paper, 2023). "Prior association of ATG4D with neurodevelopmental phenotypes in model organisms further supports a role for ATG4D in neurogenetic disease." (PMID 36765070, 2023).
ATG4D also shares sentences with these, for which no sentence is quoted: autoimmune disease (1 paper); colorectal tumors (1); cutaneous melanoma (1); gynecologic cancers (1); gynecologic tumor (1); metastatic disease (1); mucolipidosis type II (1); Multiple sulfatase deficiency (1); non-small cell lung carcinoma (1); Nystagmus (1); Obesity (1); psoriasis (1); rheumatoid arthritis (1); uterine cancer (1); uterine fibroids (1).